MIR518D (microRNA 518d)
Synonyms: hsa-mir-518d; MIRN518D
Gene: MicroRNA gene on chromosome 19 (53,734,877 to 53,734,963, forward strand). Ensembl gene ENSG00000283330.
Gene Ontology:
Biological process: miRNA-mediated post-transcriptional gene silencing
Homologues: Paralogues in human: MIR518C (92% identical), MIR523 (89% identical), MIR516A1 (87% identical), MIR518E (87% identical), MIR518F (87% identical), MIR516A2 (86% identical), MIR520C (86% identical), MIR522 (86% identical), MIR524 (86% identical), MIR518B (85% identical), MIR519A2 (85% identical), MIR520E (85% identical), and 12 more.